ERC2 (ELKS/RAB6-interacting/CAST family member 2)
Description:
Thought to be involved in the organization of the cytomatrix at the nerve terminals active zone (CAZ) which regulates neurotransmitter release. Seems to act together with BSN. May recruit liprin-alpha proteins to the CAZ.
Synonyms: KIAA0378; CAST; CAST1; SPBC110; Spc110; ELKSL
Tractability: PROTAC: ubiquitination databases record sites on it; its protein half-life has been measured.
Gene: Protein-coding gene on chromosome 3 (55,508,286 to 56,469,095, reverse strand). Ensembl gene ENSG00000187672.
Subcellular location: Cytoplasm; Synapse; Presynaptic active zone; Cytoplasm, cytoskeleton
Gene Ontology:
Molecular function: protein binding; structural constituent of presynaptic active zone
Biological process: maintenance of presynaptic active zone structure
Cellular component: growth cone; presynaptic active zone; presynaptic active zone cytoplasmic component; presynaptic membrane; cytoplasm; cytoskeleton; presynapse; synapse
Genetic constraint (gnomAD): Loss-of-function variants: 42 observed, 114.19 expected, observed/expected ratio (o/e) 0.37, 90% interval 0.29 to 0.48. The upper end of that interval is the gene's LOEUF score, 0.48, which puts it in group 2 of 6, group 1 being the genes least tolerant of losing a copy. Missense variants: 939 observed, 1,193.7 expected, observed/expected ratio (o/e) 0.79, 90% interval 0.75 to 0.83. Synonymous variants: 454 observed, 445.57 expected, observed/expected ratio (o/e) 1.02, 90% interval 0.94 to 1.1.
Homologues: Orthologues: chimpanzee ERC2 (99% identical), dog ERC2 (99% identical), macaque ERC2 (99% identical), pig ERC2 (99% identical), mouse Erc2 (99% identical), guinea pig ERC2 (99% identical), rabbit ERC2 (98% identical), rat Erc2 (98% identical), tropical clawed frog erc2 (83% identical), zebrafish erc2 (80% identical), Caenorhabditis elegans elks-1 (23% identical). Paralogues in human: ERC1 (72% identical).
Diseases named in the same sentence as ERC2 in open-access papers:
ERC2 is named in the same sentence as 23 diseases in open-access papers, as found by Europe PMC text mining. Sharing a sentence is not in itself a finding about the gene and the disease. The quoted sentences say what the papers report.
autism (2 papers, 2011 to 2021). Persistent deficits in social interaction and communication and interaction as well as a markedly restricted repertoire of activity and interest as well as repetitive patterns of behavior. "Hub genes of the turquoise module included one GABA receptor encoding genes such as Gabrb1, one glutamate receptor gene (Grid2) and genes tightly associated with synaptic development and autism (Nrxn1, Lrfn5, Plcb1, Erc2, Frmpd4, Tanc2, Ctnnd2, Dmd)." (PMID 34021132, 2021).
Obesity (2 papers, 2024). Accumulation of substantial excess body fat. "Others among the top 10% high-scoring genes with an unknown role in the context of obesity include ERC2 (23.8), ZNF131 (23.8), NLGN1 (22.8), MLTT10 (22.8), RERE (22.8), and PDCH9 (22.8)." (PMID 38754426, 2024).
scoliosis (2 papers, 2022 to 2023). A congenital or acquired spinal deformity characterized by lateral curvature of the spine. "In addition, upregulation of ERC2 and MAFB gene expression in AIS patients may promote hypertrophy of the ligamentum flavum to adapt to mechanical stresses generated by scoliosis via the TGF-β pathway." (PMID 38322243, 2023).
cardiomyopathies (1 paper, 2022). "ERC2, part of the Rab interacting molecule (RIM) family of proteins, has not been found in the context of cardiomyopathies." (PMID 35980883, 2022).
Enchondromatosis (1 paper, 2021). Enchondromatosis is a rare primary bone dysplasia disorder characterized by the development of multiple mainly unilateral or asymmetrically distributed enchondromas throughout the metaphyses of the long bones. "Our results suggest that while IDH1 is a known pathogenic gene in enchondromatosis, ERC2 is a novel gene identified in Maffucci’s syndrome." (PMID 34790172, 2021). "Our results demonstrate the impact of the ERC2 L309I mutation on the development of hemangiomas, which may be an essential factor in the transformation of enchondromatosis into Maffucci’s syndrome." (PMID 34790172, 2021).
hemangioma (1 paper, 2021). A benign vascular lesion characterized by the formation of capillary-sized or cavernous vascular channels. "Initial functional studies suggest that the IDH1 R132C mutation is likely the primary mutation responsible for the development of enchondromas, while the ERC2 L309I mutation is probably a causative mutation underlying the pathogenesis of hemangiomas." (PMID 34790172, 2021). "To demonstrate the impact of the ERC2 L309I mutation on the development of hemangiomas, we checked its role in angiogenesis, as hemangiomas are characterized by excessive vessel formation." (PMID 34790172, 2021). "The somatic L309I mutation of ERC2 contributes to the pathogenesis of hypervascularization to facilitate the development of hemangiomas in Maffucci’s syndrome." (PMID 34790172, 2021).
Hernia (1 paper, 2022). "Evidence for shared susceptibility was further provided at nine loci including 2p21 (THADA), 3p14.3 (ERC2), 3p13 FOXP1, 4q34.1 (HAND-AS1), 5p15.33 (CEP72), 7p15.2 (LOC646588), 7q33 (CALD1) and 9q22.31 (BARX1) of which eight were previously discovered on individual hernia GWAS analyses." (PMID 36584111, 2022).
kidney cancer (1 paper, 2021). Primary or metastatic malignant neoplasm involving the kidney. "Studies have also reported that genetic aberrations of ERC2 accelerate tumor formation in the body, such as kidney cancer and pancreatic cancer." (PMID 34790172, 2021).
Maffucci syndrome (1 paper, 2021). Maffucci syndrome is a very rare genetic bone and skin disorder characterized by multiple enchondromas, leading to bone deformities, combined with multiple dark, irregularly shaped hemangiomas or less commonly lymphangiomas. "Collectively, these data suggest that the IDH1 R132C mutation combines with the ERC2 L309I mutation to cause the development of Maffucci’s syndrome." (PMID 34790172, 2021). "In contrast, the ERC2 (L309I) mutation was a novel discovery, and its impact on the pathogenesis of Maffucci’s syndrome is entirely unknown." (PMID 34790172, 2021). "Therefore, our results suggest that the R132C mutation in IDH1 and the L309I mutation in ERC2 are probably the causative factors contributing to the development of Maffucci’s syndrome." (PMID 34790172, 2021). "The combination of the IDH1 R132C and ERC2 L309I mutations contributes to the development of Maffucci’s syndrome, and these results may enable further research on the pathogenesis of Maffucci’s syndrome." (PMID 34790172, 2021). "In summary, by a comparative analysis of exome sequences between peripheral blood DNA and enchondroma DNA in a patient with Maffucci’s syndrome, we identified an R132C mutation in the IDH1 gene and an L309I mutation in the ERC2 gene." (PMID 34790172, 2021).
renal cell carcinoma (1 paper, 2021). "In renal-cell carcinomas, frequent genetic and transcriptional inactivation of ERC2 occurs, suggesting that ERC2 may be involved in cancer progression." (PMID 34917133, 2021).
tumor (3 papers, 2014 to 2022). "An integrated bioinformatics analysis including 57 GBM cases and 22 cases of normal brain tissue found the Brp human orthologue ERC2 upregulated in tumor samples." (PMID 35877760, 2022).
ERC2 also shares sentences with these, for which no sentence is quoted: Alzheimer disease (2 papers); bipolar disorder (2); schizophrenia (2); Anxiety (1); cancer (1); chondroma (1); depression (1); diabetes (1); neuroblastoma (1); pancreatic cancer (1); Parkinson disease (1); psychiatric disorder (1).